LEP (leptin)
Diseases named in the same sentence as LEP in open-access papers (continued):
Sharing a sentence is not in itself a finding about the gene and the disease.
Obesity (continued). "These phenotypic characteristics are in contradiction to those of patients homozygous for mutations that inactivate leptin or the leptin receptor, which develop early onset obesity and IHH." (PMID 23248615, 2012). "In conclusion, our study revealed that a functional common genetic variant in the gene locus encoding PEDF contributes to overall body adiposity, obesity-related insulin resistance, and circulating leptin levels in humans at increased risk for type 2 diabetes." (PMID 22457810, 2012). "Consistent with previous studies, obesity caused an increase in leptin expression in both HFD-fed groups." (PMID 22778716, 2012). "The present study describes the effects of leptin deficiency-induced obesity on the distribution of mast cells in subcutaneous and visceral fat depots and regional lymph nodes." (PMID 22313574, 2012). "When stratifying, high leptin concentrations were associated with lower zinc and vitamin C concentrations in women with obesity and with high body fat percent, and were also associated with higher vitamin A concentrations in women without obesity." (PMID 22703731, 2012). "Deficiency in receptors for leptin (LepRdb-db and Leprdb-lb) in mice likewise result in obesity, diabetes, pre-diabetes, and MetS." (PMID 23369448, 2012). "The study reveals association of AMD1 variant rs2796749 with obesity, measures of adiposity and plasma leptin levels in urban Indian children." (PMID 22496743, 2012). "Meanwhile, increased levels of endogenous hormones associated with overweight and obesity, such as sex steroids, insulin, insulin-like growth factor I, and leptin, have been described as potential mechanisms linking obesity to prostate cancer." (PMID 22690216, 2012). "Our rodent model of life-long maternal obesity is characterized by the well accepted hallmarks associated with obesity such as elevated serum leptin and triglycerides and increased body fat." (PMID 22442686, 2012). "In humans at increased risk for type 2 diabetes, a functional common genetic variant in the gene locus encoding PEDF contributes to overall body adiposity, obesity-related insulin resistance, and circulating leptin levels." (PMID 22457810, 2012). "Increased leptin is associated with the inflammatory process and possibly the entire increased morbidity of obesity." (PMID 22485140, 2012). "Genetic deficiency in the gene encoding for leptin or its receptors provokes severe obesity and diabetes mellitus." (PMID 22910888, 2012). "Here, we explored the effects of leptin deficiency-induced obesity on the density of mast cells in metabolic (abdominal fat depots, skeletal muscle, and liver) and lymphatic (abdominal lymph nodes, spleen, and thymus) organs." (PMID 22313574, 2012). "Leptin, an adipokine that regulates energy balance through a wide range of systemic functions, is associated with obesity and insulin resistance." (PMID 22748134, 2012). "This is reminiscent of findings in leptin-deficient ob/ob mice, showing that circadian disruption precedes the development of obesity in these animals." (PMID 22629359, 2012). "Similar to mouse models, mutations in human leptin and/or leptin receptor genes are associated with early-onset childhood obesity." (PMID 23028384, 2012). "We show that FGF19-7 is equally efficacious as wild type FGF19 in regulating glucose, lipid, and energy metabolism in both diet-induced obesity and leptin-deficient mouse models." (PMID 22457778, 2012). "Studies in rats show that the intake of physiological doses of leptin during the suckling period prevents the animals from overweight and obesity and other metabolic alterations associated with feeding a high-fat diet." (PMID 23189059, 2012). "Fat gain depends, inter alia, on a lack of physical activity which brings to muscle loss and increased leptin levels which, in turn, support muscle loss and fat gain, leading to cachectic obesity." (PMID 22701480, 2012).
Obesity (continued). "This study demonstrates that leptin deficiency-induced obesity is accompanied by alterations in the density of mast cells in abdominal fat depots." (PMID 22313574, 2012). "Using a leptin-deficient mouse model of obesity (ob/ob), we show increased hypothalamic 5-HT1A receptor expression as well as increased hippocampal 5-HT1A, 5-HT1B, and 5-HT6 receptor mRNA expression in obese mice compared to lean control mice." (PMID 22448217, 2012). "Disturbed leptin action is implicated in both obesity and depression and altered circulating levels of leptin have been reported in both clinical HD and rodent models of the disease." (PMID 23251447, 2012). "In line with that data, leptin administration in both pregnancy and lactation has been shown to provide long-term protection from early maternal low-protein-associated obesity in rats." (PMID 23251802, 2012). "Hypothalamic leptin-melanocortin system is critical for energy balance in humans, because disruption of this network causes the most severe obesity phenotypes." (PMID 22474595, 2012). "The ob/ob mouse, a leptin protein deficient strain, is one of the most widely used mouse model of obesity and is characterised by several metabolic and neuroendocrine abnormalities, including a prominent hyperphagia leading to obesity." (PMID 22448217, 2012). "The paradoxical reduction of dopamine function associated with obesity despite reduced sensitivity to leptin/insulin is likely a (pathological) adaptation as well, as frequently proposed in theories likening obesity to addiction." (PMID 22833718, 2012). "We further tested the ability of FGF19-7 to regulate glucose metabolism in vivo in both a diet-induced-obesity (DIO) murine model as well as leptin deficient ob/ob mice." (PMID 22457778, 2012). "The high penetrance differentiates CNV-associated obesity from SNP associated obesity in which, except for some very rare mutations in a few genes of the leptin/melanocortin pathway (LEP, MC4R, etc.), almost all variants have low penetrance." (PMID 22654670, 2012). "Further, experimental and genetic interventions that block the hypothalamic NF-κB signaling reversed hypothalamic insulin and leptin resistance and was associated with reduced food intake and weight loss in the high-fat-induced obesity." (PMID 22844271, 2012). "In conclusion, our results show that Arg16Gly polymorphism plays a major role in pathogenesis of obesity, affecting lipid phenotypes, leptin levels, and insulin resistance, in individuals with different genotypes." (PMID 23056045, 2012). "Genetic deficiency of leptin or LEPRb results in hyperphagia and severe obesity in both rodents and humans." (PMID 22359610, 2012). "Although ob/ob and db/db mice are extensively used for studies of obesity-related pathophysiology, mutations in the leptin gene (ob/ob) or its receptor (db/db) are rarely described in humans." (PMID 23056561, 2012). "Obesity often manifests with hyperleptinemia, associated with leptin resistance, leading to different central and peripheral adverse effects, including increased hunger and reduced energy expenditure as well as increased lipid accumulation." (PMID 22844426, 2012). "In the present study, low vitamin C concentrations were associated with obesity and with higher leptin concentrations." (PMID 22703731, 2012). "We used two obese models, the NZO as a model for polygenic obesity and the ob/ob mouse, carrying the leptin mutation on the C57BL/6 background, because both mice differ in their shape." (PMID 22615880, 2012). "Deficiency of leptin and its receptor leads to severe obesity, insulin resistance, and diabetes in rodents and humans." (PMID 22675349, 2012). "Leptin deficiency-induced obesity was accompanied by a 20-fold increase in the density of mast cells in epididymal fat, but a 13-fold decrease in inguinal fat." (PMID 22313574, 2012).
Obesity (continued). "Children with DS have elevated serum leptin coupled with leptin resistance, both of which contribute to the obesity risk common to DS patients." (PMID 22876196, 2012). "It has been shown previously that adult lesion of AgRP neurons produces a starvation phenotype, which is averted in the setting of leptin-deficient obesity." (PMID 23028821, 2012). "The effect of exogenous leptin on insulin's actions and metabolic outputs has been studied mainly in leptin-deficient patients, as well as in models of experimental diabetes or obesity." (PMID 23056516, 2012). "The main determinant of leptin levels is adipose tissue mass, and hyperleptinemia has been linked with obesity." (PMID 22927962, 2012). "In particular, the leptin G–2548A promoter polymorphism (LEP G–2548A) [rs7799039] has been strongly associated with the serum leptin levels in overweight individuals and obesity and an increased risk for obesity." (PMID 23176367, 2012). "When stratifying by BMI and body fat percent, zinc and vitamin C concentrations were negatively associated with leptin concentrations in women with obesity and with 36-40% body fat (p < 0.05)." (PMID 22703731, 2012). "Noteworthy is that leptin deficient mice exhibit hyperplasia partly due to increased concentrations of other obesity-associated endocrine and mitogenic factors such as insulin and IL-6." (PMID 23216800, 2012). "When stratifying by BMI, % body fat and waist circumference, high leptin concentrations were associated with lower zinc and lower vitamin C concentrations in women with obesity (p < 0.05) and higher vitamin A concentrations in women without obesity (p < 0.01)." (PMID 22703731, 2012). "Obesity is associated with increased leptin levels; as a result, it has been postulated that the apparent decrease in anorexigenic effects and weight loss are the result of a mechanism of resistance to it." (PMID 21686173, 2011). "Recessive forms of obesity caused by homozygous / heterozygous compound loss of function mutations in five genes (LEP, LEPR, POMC, PCSK1 and MC4R) have been reported to date." (PMID 22043164, 2011). "Its response to leptin and the proposed relationship of this ATP hydrolytic activity with dietary-induced and obesity-associated hypertension is of particular interest." (PMID 21747933, 2011). "To do this, we utilized OB/OB knockout mice, in which a mutation in the leptin gene results in profound obesity." (PMID 21407813, 2011). "More detailed studies of the epigenetic changes associated with leptin resistance in obesity are warranted to gain insight into the link between n-3 PUFAs and obesity." (PMID 21609458, 2011). "For instance, the genetic leptin-deficient (ob/ob) or leptin-resistant (db/db) mouse are frequently used to study metabolic pathologies, e.g., obesity, insulin resistance, and diabetes." (PMID 22029623, 2011). "Leptin resistance or insensitivity has been uncovered as a cause of obesity, and in addition the leptin signalling system is less potent in the elderly." (PMID 22013440, 2011). "Assuming that insulin resistance and the obesity being the central pathogenic factor in the development of MS, a recent study reported the role of leptin, an adipokine associated with obesity, on the prediction of MS and CVD risk." (PMID 22129309, 2011). "In a leptin-deficient (ob/ob) mouse model for obesity, mice weighed twice as much as lean mice but had lower femoral bone mineral density, cortical thickness, and trabecular bone volume." (PMID 21676245, 2011). "Elevated serum leptin concentration is a feature of obesity and abdominal adiposity, a risk factor for metabolic syndrome." (PMID 21526991, 2011). "In three murine models of obesity including leptin deficient ob/ob mice, leptin receptor deficient db/db mice and KKAy44 mice, miR-335 was found to be upregulated." (PMID 21506921, 2011).
Obesity (continued). "States of congenital leptin deficiency because of mutations of the leptin gene have been associated with severe obesity, glucose intolerance, diabetes, and insulin resistance in humans." (PMID 21760816, 2011). "The leptin-deficient (fa/fa), hyperphagic Zucker Diabetic Fatty rat develops overt obesity and severe hepatic and peripheral insulin resistance and is a commonly used animal model of T2D." (PMID 22087313, 2011). "It is of interest to note that mutagenesis of this tyrosine residue leads to adult-onset obesity linked to leptin resistance in mice." (PMID 22013440, 2011). "Decreased leptin levels have been shown to cause obesity; however, it also reflects a decrease in total body fat mass." (PMID 21826185, 2011). "In ob/ob mice, a loss of function mutation in the ob gene that encodes leptin leads to obesity by around four weeks of age." (PMID 22013440, 2011). "Disturbances in leptin and insulin signaling pathways are related to obesity and metabolic syndrome (MS) with increased risk of diabetes and cardiovascular disease." (PMID 22185674, 2011). "Heterozygosity for deleterious coding mutations in MC4R or POMC has been associated with a non fully penetrant form of obesity, whereas partial LEP or LEPR deficiency has been associated with a higher percentage of body fat mass." (PMID 22043164, 2011). "Secondly, olanzapine was associated with increased concentrations of leptin and triglycerides, factors consistently elevated in obesity and diabetes." (PMID 21857944, 2011). "In mice, mutations of the OB gene on chromosome 7, which encodes the leptin protein, results in obesity and type 2 diabetes." (PMID 21526991, 2011). "Recent data showed that the obesity induced by leptin deficiency upregulated the expression of TLR1-9 and TLR11-13 in murine adipose tissues." (PMID 21960997, 2011). "Leptin levels in synovial fluid are correlated with BMI; thus, it is a possible metabolic factor in OA pathogenesis, appearing to mediate obesity- and sex-related knee cartilage loss." (PMID 20482813, 2010). "Several animal models of monogenic obesity involve mutations in leptin (Leptinob/ob mice) or its receptors (Leprdb/db mice and fa/fa rats)." (PMID 21151569, 2010). "Whereas the B1R is associated with leptin resistance and obesity, its beneficial or detrimental role in cardiac ischemia remains conflicting and recently, B1R was found implicated in renal fibrosis." (PMID 20830306, 2010). "Using the random ENU-mutagenesis, we created a novel mouse model inherited in a recessive pattern for obesity and insulin resistance due to a missense V145E mutation in the Leptin gene." (PMID 21151569, 2010). "Among LEPTIN mutations reported thus far in human obesity, ΔG133 and R105W mutations result in an inability to produce/secrete the leptin protein, with undetectable levels in the serum of affected individuals." (PMID 21151569, 2010). "Leptin deficiency in humans either due to an absolute shortage of leptin or due to leptin-receptor mutations causes severe early onset obesity, hyperphagia, hyperinsulinemia, hypogonadism, and impaired T cell function." (PMID 20871818, 2010). "As such, leptin levels are directly proportional to BMI and patients deficient in either leptin or leptin receptor are characterized by marked obesity." (PMID 20585554, 2010). "Obesity is indeed associated with leptin resistance and obese subjects show highly elevated serum concentrations of leptin." (PMID 20414467, 2010). "It was shown that leptin increases the gastrocnemius weight and reduces the high expression levels of genes related to the obesity-associated low-grade inflammation in skeletal muscle of ob/ob mice." (PMID 20671928, 2010). "Studies have demonstrated leptin to be an independent risk factor for stroke and myocardial infarction after controlling for obesity status." (PMID 20706676, 2010). "Human obesity is associated with increased circulating leptin levels and a relative leptin "insensitivity"." (PMID 21040518, 2010).
Obesity (continued). "The V145E mutation of leptin leads to a phenotype of extreme obesity, characterized by adipocyte hypertrophy and hyperplasia, positive energy imbalance, and liver steatosis." (PMID 21151569, 2010). "Plasma leptin correlates with BMI, and weight loss reduces its circulatory concentrations in a variety of human disorders associated with obesity." (PMID 20414465, 2010). "The mouse model harboring leptin V145E mutation will serve as an excellent model for human obesity which results from leptin dysfunction." (PMID 21151569, 2010). "While some studies have indicated that circulating leptin levels are not significantly related to the risk of CVD or mortality in a diabetic population, these studies did find that leptin was associated with obesity and inflammatory markers." (PMID 20847813, 2010). "In contrast to leptin-deficient ob/ob mice, plasma leptin concentration is significantly elevated in animals with dietary-induced obesity as well as in obese humans reflecting the state of hypothalamic leptin resistance." (PMID 21286276, 2010). "The underlying genetic defect in leptin signaling in the animals additionally causes hyperphagia, hyperinsulinemia, hyperglycemia and a marked obesity." (PMID 21318183, 2010). "Increased circulating leptin, a marker of leptin resistance, is common in obesity and independently associates with insulin resistance and CVD in humans." (PMID 20482839, 2010). "This is due mainly to the fact that a very small fraction of the obese human population is leptin deficient, and the most common forms of obesity are associated with high leptin levels." (PMID 20808936, 2010). "As human obesity is associated with hyperleptinemia and atherosclerosis, it was shown that leptin, in addition to its angiogenic properties, exerts proatherogenic effect on endothelial cells by increasing reactive oxygen species (ROS) formation." (PMID 20170522, 2010). "Higher leptin levels were confined to the variants of Q223R, which confirms that the QR and RR are highly associated with obesity, since the leptin resistance is the prime characteristic of the obesity." (PMID 21031055, 2010). "In humans and rodents, mutations of the gene encoding leptin lead to severe early-onset obesity, which can be corrected by leptin treatment." (PMID 20652026, 2010). "Although association of obesity, leptin, ghrelin, and inflammations well documented, role of adipokines and ghrelin in OSAS remains controversial." (PMID 20835311, 2010). "The Clock mutant mouse has altered feeding patterns accompanied by the development of obesity and elevated TG, glucose and leptin levels, and mutations in Clock and Bmal influence the diurnal variation in TG and glucose concentrations." (PMID 20961464, 2010). "I characterize physiological effects of leptin as well as its involvement in obesity-associated hypertension." (PMID 21286276, 2010). "Because the expression levels of many genes in various metabolic pathways are affected by obesity, we generated leptin and FSP27 double deficient mice (ob/ob/FSP27-/-) and examined the expression levels of BAT-selective genes in the WAT of these animals." (PMID 20649970, 2010). "We corroborated that in women leptin concentration is higher than in men and the relationship between circulating leptin and obesity, decreasing significantly serum leptin concentration after weight loss." (PMID 20380714, 2010). "For example, in mice, mutations in the leptin gene cause early-onset, extreme obesity and the same is true for humans." (PMID 20860848, 2010). "Obesity is an important cofactor in type 2 diabetes because the presence of obesity and diabetes together is associated with more severe insulin and leptin resistance than either condition alone." (PMID 20181219, 2010). "Adipocyte enlargement, as observed in obesity, is associated with dysfunctional fat cells which over-express and secrete excessive amounts of leptin, IL-6, TNFα, resistin, MCP-1 and FFA while under secreting adiponectin." (PMID 19656356, 2009).